CXCL10 (C-X-C motif chemokine ligand 10)
Diseases named in the same sentence as CXCL10 in open-access papers (continued):
Sharing a sentence is not in itself a finding about the gene and the disease.
psoriasis (continued). "IFN-γ is a notable cytokine in psoriatic lesions that can induce the upregulation of Th1 and dendritic cells chemokines, such as CXCL10 and CCL2, which are expressed prominently in psoriasis." (PMID 33149756, 2020). "A comparative analysis showed that the percentage of inflammatory cells expressing CXCL10 in skin lesions from AOSD patients was significantly greater than that in normal controls (p = 0.012) and patients with eczema (p = 0.019) or psoriasis (p = 0.009)." (PMID 28436448, 2017). "First, the percentage of CXCL10-positive inflammatory cells in the skin of AOSD patients was significantly higher than that in normal skin and skin from eczema and psoriasis patients." (PMID 28436448, 2017). "The mean percentages of inflammatory cells from psoriasis skin lesions expressing CXCL9, CXCL10, CXCL11 and CXCR3 were 3.0% ± 3.4%, 3.0% ± 2%, 46.8% ± 17.7% and 21.2% ± 19.5%, respectively." (PMID 28436448, 2017). "In conclusion, we demonstrate that the cytokines-mediated overexpression of IFI16 contributes to the pathogenesis of psoriasis by activating the TBK1-NF-κB signaling pathway and then inducing the production of CXCL10 and CCL20 in keratinocytes." (PMID 27137868, 2016). "CXCL10 and CXCR3, which were both up-regulated in the periadnexal areas of DLE versus psoriasis lesional skin, appeared to mimic the expression patterns of effector T cells and macrophages." (PMID 24744689, 2014). "CXCR3, CXCL10, and TIA-1 were elevated in periadnexal sites of DLE lesional skin versus psoriasis lesional skin." (PMID 24744689, 2014). "In addition to those previously noted, cytokines like IFN-γ, TGF-β, CXCL9, CXCL10, IL-33 and CXCL11 play a significant role in psoriasis pathogenesis." (PMID 40303401, 2025). "Recent research suggests that estrogen affects the expression of immune cells (DCs and γδT cells), chemokines (CCL5 and CXCL10), and cytokines (TNF-α, IL-23, and IL-17 family), which worsens cutaneous inflammation in psoriasis and provides new insights for developing treatment strategies." (PMID 40303401, 2025). "Its ligand, CXCL10, is considered as a predictive biomarker of PSA in patients with psoriasis." (PMID 37492568, 2023). "Similar to other related immune-mediated skin disorders, such as psoriasis, the miRNA17-92a-1 cluster promotes chemokines, such as CXCL9 and CXCL10, in keratinocytes and further T cell chemotaxis by inhibiting the expression of suppressor of cytokine signaling 1 (SOCS1)." (PMID 35328059, 2022). "The dysfunction in psoriasis includes systemic inflammation involving cytokines, such as IL-17, TNF-α and IFN-γ, as well as inflammatory transcripts such as CXCL10, IL-1β and VCAM-1.Psoriasis increases vascular stiffness and atherosclerosis tthrough the IL-17 pathway." (PMID 36211578, 2022). "Finally, PPI network analysis demonstrated that CXCL10 was the hub gene with the highest degree, and CXCR2, CXCL10, IVL, OASL, and ISG15 were the potential gene targets of the drugs for treating psoriasis." (PMID 32669126, 2020). "While the marker cytokines of psoriasis were virtually non-detectable in non-lesional skin, chemokines CXCL10 and CCL20, the respective chemoattractants for Th1 and Th17 cells, were significantly increased." (PMID 28790368, 2017). "On immunohistochemistry, the percentage of CXCL10-positive inflammatory cells was higher in skin biopsy samples from AOSD patients than in those from normal control (p = 0.012), eczema (p = 0.019), and psoriasis (p = 0.009) groups." (PMID 28436448, 2017). "Psoriasis patients who subsequently developed PsA had higher levels of CXCL10 in the serum than those who did not develop PsA." (PMID 27928500, 2016). "CXCL10 appears to be important for leukocyte trafficking that leads to increased tissue inflammation and may be overexpressed in CD4 + T helper 1 (Th1)-mediated inflammatory diseases like multiple sclerosis and psoriasis." (PMID 39924511, 2025).
psoriasis (continued). "In a study conducted in patients with psoriasis and atopic dermatitis, reductions of CD56bright NK cells were connected with the previous findings of accumulated CXCR3 expressing CD56bright NK cells in lesional skin, probably due to CXCL10 production by psoriatic keratinocytes." (PMID 37744329, 2023). "Besides, some psoriasis-related genes such as SPRR genes, HSD11B1, GGH, CXCR2, IVL, OASL, ISG15, and CXCL10 may be important targets in psoriatic therapy." (PMID 32669126, 2020). "The percentage of inflammatory cells expressing CXCL10 in AOSD patients was higher than that in normal control, eczema, and psoriasis groups, but the percentage of inflammatory cells expressing CXCL11 in AOSD patients was lower than that in eczema and psoriasis patients." (PMID 28436448, 2017). "Additionally, expression of CCL2 mRNA was significantly induced, and there were mild (but not statistically significant) increases in CXCL1, CXCL10, CCL5, and IL-8 in psoriasis-associated mutant CARD14 transfected HDBECs compared to wild-type HDBECs." (PMID 25369198, 2014). "Notably, some of them, including CXCL9 and CXCL10, are upregulated even in non-lesional skin of psoriasis patients which may contribute to the initiation of novel skin lesions." (PMID 38642273, 2024). "In psoriasis, estrogen might exert its functions by modulating the expression of certain genes like sex-biased transcription co-factor vestigial-like protein 3 (Vgll3) and CCAAT enhancer binding protein beta (cebpb), microRNAs (miR146a, 21 and 210), and chemokines (CCL5 and CXCL10)." (PMID 35663991, 2022). "Importantly, CXCL10 and CCL20 expressions were decreased in the psoriasis-like lesions in the absence of p204, which was accompanied by a decrease in the phospho-p65 level and inhibition of p65 nuclear translocation in epidermal cells." (PMID 27137868, 2016). "Psoriasis-specific cytokines (e.g., IL-12, IL-17A, IL-23) did not promote chemokine expression, but TNF-α – which could indicate both infection and sterile inflammation – was able to induce CCL-2 and CXCL10 expression." (PMID 41264606, 2025).
pneumonia (70 papers, 2011 to 2025). An acute, acute and chronic, or chronic inflammation focally or diffusely affecting the lung parenchyma, caused by an infection in one or both of the lungs (by bacteria, viruses, fungi, or mycoplasma.). "CXCL10 levels on hospital admission have been associated with severe pneumonia outcomes." (PMID 41307734, 2025). "CXCL10, a key interferon-induced chemokine which attracts activated T-cells, NK cells, and monocytes to the site of infection, is implicated in acute lung injury and correlates with poor pneumonia outcomes." (PMID 40869413, 2025). "In agreement with previous studies, this study found higher CXCL10 levels in patients with severe pneumonia than in patients with moderate pneumonia, and significant elevation in patients developing MAS and fatal cases." (PMID 37493737, 2023). "Moreover, IL-6 and CXCL10 levels were significantly associated with the presence of pneumonia and the development of respiratory failure, thereby supporting the hypothesis that the elevation of these inflammatory biomarkers is possibly dominant in the pulmonary circulation." (PMID 35237279, 2022). "In line with several other publications, we showed that CXCL10 is increased in the blood of patients with active TB and pneumonia, as compared to healthy volunteers." (PMID 30026741, 2018). "In controls, CXCL10-positive staining was found in macrophages in alveolar spaces, while in pneumonia samples, CXCL10-positive histiocytes were found in inflammatory exudates." (PMID 30026741, 2018). "TB patients had significantly higher levels (p < 0.0255) of all forms of CXCL10 (CXCL10total) compared to that found in patients with pneumonia and controls." (PMID 30026741, 2018). "The quantitative assessment of CXCL10 showed high labeling score (score 4 in majority of cases) in TB with respect to controls and pneumonia cases." (PMID 30026741, 2018). "The levels of IL-6 and CXCL10 were higher in children with PFAPA during febrile episodes than in children with pneumonia." (PMID 24134207, 2013). "The levels of CXCL10 remained higher in children with PFAPA between febrile episodes compared to children with pneumonia after recovery." (PMID 24134207, 2013). "The levels of CXCL10 and IL-6 were significantly higher in patients with pneumonia and hypoxemia." (PMID 35237279, 2022). "The serum levels of inflammatory cytokines, IL-6 and CXCL10, were significantly associated with pneumonia and hypoxemia, but not with the viral load in nasal-swab specimens." (PMID 35237279, 2022). "Evidence also suggests that when people are infected with some severe respiratory viruses (such as SARS-CoV, H5N1), neutrophil infiltration into the lungs will produce high levels of chemokines, such as C-X-C motif chemokine 10 (CXCL10), which can induce fulminant pneumonia and aggravate the ARDS." (PMID 33602128, 2021). "Upregulation of CXCL10 also coincided with the peak of chest infiltrates and severity of pneumonia." (PMID 33613280, 2020). "The greater expression of interferon-induced genes in S. pneumoniae infection was also reflected at the protein level as shown by the significantly higher amounts of interferon-induced CXCL9 and CXCL10 in serum of S. pneumonia-infected mice in comparison with S. aureus-infected or PBS-treated mice." (PMID 29988532, 2018). "The levels of serum cytokines including CXCL10, IL-2, and TNF-α appeared to be correlated with the severity of pneumonia." (PMID 36949406, 2023). "Associations of PM2.5, NO2, SO2, and O3 with the log-transformed LDH, total protein, CXCL10, IFN-γ, CD14, and CD62 levels in pleural effusion were determined after adjusting for age, sex, BMI, smoking, and disease category (pneumonia or CHF)." (PMID 30818785, 2019). "There was sustained activation of the proinflammatory cytokines (IL-6, CXCL8/IL-8, CCL2/MCP-1, sTNFR-1) in severe pH1N1 pneumonia; the CXCL10/IP-10, CXCL9/MIG and IL-17A responses remained largely suppressed during the hospital course." (PMID 22022504, 2011).
pneumonia (continued). "The adaptive-immunity (Th1/Th17)-related CXCL10/IP-10, CXCL9/MIG and IL-17A however, were markedly suppressed in severe pH1N1 pneumonia (2–27 times lower than seasonal influenza; P−values<0.01)." (PMID 22022504, 2011). "IL-6 and CXCL10 levels were higher in patients with pneumonia than in those without it, regardless of their vaccination status." (PMID 38694512, 2024). "In the comparison between vaccinated and unvaccinated patients with pneumonia, the levels of IL-6, CXCL10, LD, IFN-α, IFN-λ1, IFN-λ3, VEGF, and NLR were not different." (PMID 38694512, 2024). "In addition to the biomarkers that were associated with the development of hypoxemia (IFN-α, IL-6, CXCL10, LDH, and CRP), VEGF, NLR, and adjusted NT levels were significantly higher in patients with pneumonia than in those without pneumonia." (PMID 37731495, 2023). "Immunohistochemical assays were performed to evaluate CXCL10 expression in lung specimens taken post-mortem from patients with active TB (mycobacterial DNA demonstrated by PCR, data not shown), pneumonia and patients with diffuse alveolar damage related to cardiac failure." (PMID 30026741, 2018). "The levels of IL-6, CXCL10, LD, and CRP were significantly higher in patients with pneumonia than in those without pneumonia, both in the vaccinated and the unvaccinated group." (PMID 38694512, 2024).
atherosclerosis (68 papers, 2008 to 2025). A disease characterized by the build-up of fatty material and calcium deposition in the arterial wall resulting in partial or complete occlusion of the arterial lumen. "More specifically, these chemokines are widely recognized for their vital role in the recruitment of monocytes (CCL2), neutrophils (CXCL5/6), and lymphocytes (CXCL10), which have all been implicated in the pathogenesis of atherosclerosis." (PMID 39201392, 2024). "Increased serum levels of CCL5 and CXCL10 are associated with human atherosclerotic plaque progression and stability, and the inhibition of either cytokine reduced atherosclerosis in animal models." (PMID 36247423, 2022). "IP-10 (also called CXCL10) plays a significant role in leukocyte homing to inflamed tissues, and increased IP-10 levels are associated with the pathologies of various inflammatory disorders, including type 2 diabetes, atherosclerosis, and cancer." (PMID 34572567, 2021). "In CXCL10-knocked out/apolipoprotein E-deficient mice, the atherosclerosis progression was shown to be well-correlated with enhanced Treg cell numbers and their subsequent effect on the reduction of atherosclerotic lesion formations." (PMID 34835155, 2021). "To provide evidence that the findings in the mouse bear relevance for human atherosclerosis, we also investigated the association between CXCL10 concentrations and plaque composition in human carotid endarterectomy lesions." (PMID 22164344, 2011). "Recently, it has been reported that genetic deletion of CXCL10 in atherosclerosis susceptible mice also resulted in smaller lesions, which contained fewer CD4+ T cells." (PMID 22164344, 2011). "Thus, further work is required to understand the molecular mechanism underlying CXCL10 functions in atherosclerosis, especially the implication of GAG-trapped versus free CXCL10." (PMID 31824304, 2019). "In terms of atherosclerosis, we also found that the top upregulated in the atherosclerotic Nrf2Cdh5tKO mice Cxcl10 gene, was involved in all the most enriched KEGG pathways." (PMID 37965327, 2023). "CXCL10, on the other hand, promotes atherosclerosis by regulating the ratio of effector and regulatory T cells in plaques." (PMID 38201205, 2023). "It was also proven to inhibit epidermal growth factor receptor (EGFR) which resulted in the activation of atherosclerosis and CXCL10/IP-10 which then further activates atherosclerosis." (PMID 37569355, 2023). "CXCL10 is a chemokine expressed at all stages of atherosclerosis, participating in VSMC proliferation and intimal hyperplasia." (PMID 38268851, 2023). "In ApoE−/− mice studies, blocking CXCL-10 was shown to inhibit the formation of atherosclerosis and resulted in the development of a more stable plaque phenotype." (PMID 37569355, 2023). "GDF-15 and CXCL10 are proatherogenic inflammatory markers, and they are promising biomarkers in cardiovascular diseases in humans, including atherosclerosis." (PMID 36001144, 2022). "CXCL10 acts as a chemoattractant cytokine and was shown to promote atherosclerosis by recruitment and retention of activated T lymphocytes to vascular wall lesions during the atherosclerotic process." (PMID 36001144, 2022). "Chemokines such as CCL2, CCL5, and CXCL10 play a crucial role in the early stages of atherosclerosis via EBD as well as via atherogenic phenotype switching of VSMCs." (PMID 36497143, 2022). "EC, VSMCs, and macrophages all express CXCL10 during atherosclerosis while its receptor CXCR3 is mainly expressed on CD4+ T cells." (PMID 35600479, 2022). "The main goal of the present review is the elucidation and clarification of the role of CXCL10 as an inflammatory mediator for atherosclerosis progression and further CAD." (PMID 34835155, 2021). "Macrophage inflammatory protein 1β (MIP1β/CCL4) is a highly related member of the CC chemokine subfamily that is involved in the occurrence and development of atherosclerosis, and CXCL10 (IP-10) is a chemokine induced by IFN-γ." (PMID 33115500, 2020).
atherosclerosis (continued). "Consistently, the ApoE−/− mouse model in which CXCL10 or its receptor were invalidated displayed reduced atherosclerosis development." (PMID 31824304, 2019). "Nevertheless, our data indicate that atherosclerotic mice lacking TACI signaling in myeloid cells express increased amounts of typical TLR9-induced genes, such as Ifit2 and Cxcl10 transcripts, in their spleens and developed increased atherosclerosis." (PMID 29858401, 2018). "CXCL10 has been shown to aggravate experimental atherosclerosis, and to be an independent prognostic factor for increased CVD risk in humans, providing a potential mechanism through which BAFF modulates atherosclerotic risk." (PMID 29858401, 2018). "Expression of key chemokines previously linked to atherosclerosis, including CCL2 and CXCL10 as well as CCL5, was significantly attenuated by AVE0991 treatment, in the PVAT of ApoE−/− mice, while no change was seen in the aortic wall itself." (PMID 27935022, 2017). "CXCL10 is known to contribute to the pathophysiology of cardiovascular disease, such as atherosclerosis, aneurysm formation, MI, and PAD, in both experimental and clinical studies." (PMID 24868552, 2014). "Shortly after this observation, mouse models for atherosclerosis revealed a role for CXCL10 in (early) lesion development." (PMID 24868552, 2014). "The involvement of CXCL10 in atherosclerosis in both experimental and clinical settings suggests that CXCL10 contributes positively to the initiation and progression of the disease." (PMID 24868552, 2014). "Of these, CXCL9, CXCL10, CCL5, CCL8, CRCL2, Cd74 and IRF8 have previously been implicated in atherosclerosis." (PMID 25478796, 2014). "Little is known about the effects of CXCL10 on human atherosclerosis development and clinical outcome." (PMID 22164344, 2011). "Despite these compelling findings described in the literature, in atherosclerosis CXCL10 has been less completely characterized." (PMID 22164344, 2011). "The chemokines CCL2 (also known as MCP-1 (monocyte chemoattractant protein-1)), CCL5, and CXCL10 (also known as IP-10 (interferon gamma-induced protein 10)) play a central role in the initiation and progression of atherosclerosis by recruiting and activating inflammatory cells." (PMID 40943241, 2025). "Additionally, studies have found that people with an eGFRcys/eGFRcr ratio <0.6 have higher levels of proteins related to atherosclerosis and cell proliferation, such as IL-6, CXCL10 and FGF23." (PMID 40235956, 2025). "The downregulation of IL4, CXCL10, MCP1, TNFα, and estradiol and CSF3 upregulation may mediate the adaptation of adiponectin-deficient males to HFD-induced atherosclerosis." (PMID 38201205, 2023). "Interestingly, treatment with CXCL10 neutralizing antibody reduced the size and stability of atherosclerotic plaques in the carotid cuff model of atherosclerosis in ApoE–/– mice." (PMID 36247423, 2022). "Future studies could investigate the role of CXCL10 on the phenotypic switching of VSMCs within atherosclerosis." (PMID 35600479, 2022). "This suggests that CXCL10 also has a paracrine relationship with endothelial healing and may play a role in maintaining endothelial dysfunction in atherosclerosis." (PMID 35600479, 2022). "For example, IP-10, encoded by CXCL10, and IL-8, encoded by CXCL8, belong to the C-X-C chemokine subfamily, and the literature is overflowing with evidence regarding their potential roles in causing atherosclerosis." (PMID 34941711, 2021). "During atherosclerosis progression, endothelial cells, macrophages, and VSMCs express CXCL10." (PMID 31824304, 2019). "Altogether, these data place CXCL10 as an attractive target for atherosclerosis therapies." (PMID 31824304, 2019). "Moreover, in terms of atherosclerosis development, IL27 is known to induce in HUVECs the upregulation of the chemokines CXCL9 and CXCL10, implicated in the transendothelial cell migration." (PMID 26663990, 2015).